SCN3A (sodium voltage-gated channel alpha subunit 3)
Diseases named in the same sentence as SCN3A in open-access papers (continued):
Sharing a sentence is not in itself a finding about the gene and the disease.
autism (4 papers, 2013 to 2020). Persistent deficits in social interaction and communication and interaction as well as a markedly restricted repertoire of activity and interest as well as repetitive patterns of behavior. "Intriguingly, rare mutations within genes encoding similar α subunits, such as SCN1A, SCN2A and SCN3A, have been linked to autism." (PMID 24564958, 2014).
developmental and epileptic encephalopathy (4 papers, 2023 to 2026). An epilepsy associated with developmental impairment that may be due to either the underlying etiology or the superimposed epileptic activity, or both. "Mutations in SCN1A, SCN2A, SCN3A, and SCN9A genes are known to cause autosomal dominant developmental and epileptic encephalopathies, with haploinsufficiency as a primary mechanism." (PMID 40894531, 2025).
neuroblastoma (4 papers, 2017 to 2024). Neuroblastoma (NB) is the most common solid, extracranial childhood tumor. "The lung cancer cells H460 only express SCN3A and SCN9A, whereas the neuroblastoma cells SHSY express SCN1A, SCN2A, SCN3A, and SCN9A." (PMID 31329011, 2019).
neuropathy (3 papers, 2016 to 2023). A disorder affecting the nervous system that manifests with pain, tingling, numbness, and/or muscle weakness. "SCN3A c.2077A > G and SCN4B c.298C > T were novel for a painful and painless neuropathy, and classified as VUS." (PMID 37175987, 2023).
Ataxia (2 papers, 2012 to 2021). Ataxia refers to impaired coordination of voluntary muscle movement. "Brain sodium channelopathies, which include mutations in SCN1A, SCN2A, SCN3A, and some mutations in SCN8A observed in cases of familial human ataxia and in mice models of ataxia and end-plate diseases (these genes encode the channels NaV1.1, NaV1.2, β1-subunit, and NaV1.6 respectively)." (PMID 22798951, 2012).
autism spectrum disorder (2 papers, 2018 to 2021). A spectrum of developmental disorders that includes autism, and Asperger syndrome. "Previous studies report a potential susceptibility region at the chromosomal locus 2q including SCN1A, SCN2A and SCN3A genes for autism spectrum disorder (ASD)." (PMID 30071822, 2018).
breast carcinoma (2 papers, 2021 to 2022). "Moreover, it has been reported that miR-106a-5p/SCN3A axis is involved in long noncoding RNA HOXA-AS2-regulated breast cancer." (PMID 33686957, 2021).
early infantile epileptic encephalopathy (2 papers, 2020 to 2025). "Heterozygous missense mutations in SCN3A have been identified as a cause of early infantile epileptic encephalopathy (EIEE), with three causative variants reported in four patients." (PMID 41007641, 2025). "While some SCN3A variants have been linked to milder phenotypes, such as focal epilepsy and generalized epilepsy with febrile seizures plus (GEFS+), there are severe forms, such as early infantile epileptic encephalopathy (EIEE)." (PMID 41007641, 2025).
neuropathic pain (2 papers, 2017 to 2020). Chronic pain caused by damage to nerve fibers. "In this study, we developed a MIPs-NGS and TSCA-NGS targeted re-sequencing panels for nine sodium channel genes (SCN3A, SCN8A-SCN11A, and SCN1B-SCN4B) known to be associated with neuropathic pain, and compared their sensitivity, specificity, targeting efficiency, performance and cost effectiveness." (PMID 32877464, 2020).
sleep disorder (2 papers, 2021 to 2022). A change from the patient's baseline sleeping pattern, in the hours slept and/or an alteration/dysfunction in the stages of sleep. "This gene is homologous with human genes SCN1A, SCN2A and SCN3A, which encode sodium channels and have been associated with neuronal and sleep disorders." (PMID 35189951, 2022).
viral infection (2 papers, 2020 to 2021). "Although SCN3A has previously not been described in the context of virus infections, DUOX1 appears to promote the innate immune defense to pathogens via the production of reactive oxygen species." (PMID 33585804, 2021).
chronic thromboembolic pulmonary hypertension (1 paper, 2023). Chronic thromboembolic pulmonary hypertension (CTEPH) is characterized by the persistence of thromboemboli in the form of organized tissue obstructing the pulmonary arteries. "Intriguingly, SCN3A was identified as a potential marker in patients with chronic thromboembolic pulmonary hypertension, and it is predicted to participate in the ion flux of pulmonary artery smooth muscle cells (PASMC), which modulates excitation and contraction of pulmonary vessels." (PMID 36835058, 2023).
colon cancer (1 paper, 2018). "Moreover, we noted that some of the mRNAs (ANLN, CFL2, FJX1, HHIP, PANX2, SCN3A, VSNL1 and ZIC2) were also associated with overall survival in patients with colon cancer." (PMID 29420609, 2018).
hearing loss (1 paper, 2016). "As a marker linked to adult neuronal function we analysed expression of SCN3A (voltage gated sodium channel type 3, alpha subunit) which in humans lies within a chromosomal locus associated with hearing loss." (PMID 26819088, 2016).
hepatoblastoma (1 paper, 2016). Hepatoblastoma (HB) is a malignant hepatic tumor and is the most common pediatric liver cancer. "Cytogenetic data of hepatoblastoma have revealed that up-regulation of GALNT5, DAPL1, ERMN, SCN1A and SCN3A plays a major role in the development and progression of the disease." (PMID 27322213, 2016). "However, the post-translational modifications regulated by GalNAcT5 in hepatoblastoma cells remain undefined, as the mechanism of action of DAPL1, ERMN, GALNT5, SCN1A and SCN3A genes." (PMID 27322213, 2016).
hereditary hemorrhagic telangiectasia (1 paper, 2026). A disorder of angiogenesis leading to arteriovenous dilatations: cutaneo-mucosal hemorrhagic telangiectasias and visceral shunting. "Dominant causes included 22q deletion syndrome, DYNC1H1, SCN3A, and hereditary hemorrhagic telangiectasia (HHT) genes, ACVRL1 and ENG." (PMID 41670011, 2026).
infantile epilepsy (1 paper, 2025). "Notably, there were also reported infantile epilepsy cases with SCN3A variants not showing PMG19,36." (PMID 39966398, 2025).
pulmonary arterial hypertension (1 paper, 2023). Pulmonary arterial hypertension (PAH) is a group of diseases characterized by mean pulmonary artery pressure >20 mmHg and elevated pulmonary arterial resistance leading to right heart failure. "Given the significance of pulmonary arterial hypertension in SSc, SCN3A warrants further consideration." (PMID 36835058, 2023).
schizophrenia (1 paper, 2022). A major psychotic disorder characterized by abnormalities in the perception or expression of reality.
Seizure (1 paper, 2023). A seizure is an intermittent abnormality of nervous system physiology characterized by a transient occurrence of signs and/or symptoms due to abnormal excessive or synchronous neuronal activity in the brain. "Seizures declined in two SCN3A patients and VPA was effective, whereas OXC was ineffective." (PMID 38174099, 2023).
status epilepticus (1 paper, 2023). Status epilepticus is defined as a continuous seizure lasting more than 30 min, or two or more seizures without full recovery of consciousness between any of them. "Except for variants SCN3A and SCN11A, some patients with other variants had status epilepticus (SE)." (PMID 38174099, 2023).
subarachnoid hemorrhage (1 paper, 2025). A serious neurological disorder characterized by intracranial hemorrhage into the subarachnoid space. "The single SCN3A patient exhibited superficial siderosis in the left parietal lobe, likely a sequela of a prior subarachnoid hemorrhage." (PMID 41573391, 2025).
Tourette syndrome (1 paper, 2018). A neurologic disorder caused by defective metabolism of the neurotransmitters in the brain. "We discuss the association of SCN2A, SCN3A, GRB14, COBLL1 and SCL38A11 deletions with ASD and Tourette syndrome and possible implications for treatment." (PMID 30071822, 2018). "To date, there is no previous description of a patient with comorbid ASD and Tourette syndrome showing a deletion containing SCN2A and SCN3A." (PMID 30071822, 2018).
Ventricular arrhythmia (1 paper, 2025). "For ventricular arrhythmia, many of the significant proteins identified by the diffusion algorithm are ion channel proteins, such as those that contribute to Ca2+ (CACNA1C, CACNA1C-IT2), Na+ (SCN3A, SCN1B, SCN4B, SCN10A), or K+ (KCNQ1, KCNE3, KCNH2) transport in the heart." (PMID 39954672, 2025).
neurodevelopmental disorder (3 papers, 2022 to 2025). A behavioral and cognitive disorder with onset during the developmental period that involves impaired or aberrant development of intellectual, motor, or social functions. "Among the DEGs, strong evidence of involvement in neurodevelopmental disorders was reported for 15 of them (“definitive” gene list from SysNDD, e.g., PLP1, RGS6, and SCN3A) and moderate evidence for 10 more (“limited” gene list from SysNDD, e.g., UNC13A, NMNAT2, and CHL1)." (PMID 40182141, 2025).
tumor (3 papers, 2019 to 2023). "By combining these gene sets, we identified the leading genes that were associated with the tumor laterality: CACNA1C, CACNA2D2, CACNB2, KCNJ11, SCN3A, and SCN3B, signature that we called: 6-ICH signature." (PMID 37446299, 2023).
cancer (2 papers, 2013 to 2024). A tumor composed of atypical neoplastic, often pleomorphic cells that invade other tissues. "No studies to date have investigated the potential connections between these gene-cancer pairs, therefore, SCN3A-LGG, SCN3B-LGG, SCN4A-KIRC, and SCN1B-PAAD would be potential clinically significant research topics for future study." (PMID 39060933, 2024). "Among these gene-cancer pairs, SCN3A-LGG, SCN3B-LGG, SCN4A-KIRC, SCN1B-UVM, and SCN1B-PAAD have a relatively high gene expression level, and have a relatively large case number except for UVM (n = 79)." (PMID 39060933, 2024). "The cell lines expressed one constitutively active Na+ channel (SCNN1A) and one voltage-gated Na+ channel (SCN3A) as well as about 200 voltage-gated K and Ca2+ channels with no major differences in the number or level of expressed ion channel genes between carcinoma cells and normal cells." (PMID 23505537, 2013).
genetic diseases (1 paper, 2017). "WES enabled timely diagnosing of genetic diseases, validation of causality of specific genetic disorders of PTPN23, KCTD3, SCN3A, PPOX, FRMPD4, and SCN1B, and setting dual diagnoses by detecting two causative variants in distinct genes in the same patient." (PMID 27848944, 2017).
heart disease (1 paper, 2018). "Multiple genes known or plausibly linked to heart development and post-natal heart disease were found to be differentially methylated in the blood DNA of newborns with TOF including: ABCB1, PPP2R5C, TLR1, SELL, SCN3A, CREM, RUNX and LHX9." (PMID 30212560, 2018).
infection (1 paper, 2017). The state of being infected such as from the introduction of a foreign agent such as serum, vaccine, antigenic substance or organism. "Sodium voltage-gated channel alpha subunit 3 (SCN3A) and two solute carriers SLC24A2 and SLC1A3 were highly altered following infection." (PMID 29085037, 2017). "Sodium voltage-gated channel alpha subunit 3 (SCN3A) and two solute carriers SLC24A2 and SLC1A3 were highly altered following infection, indicating that ion transport could be important in response to infection." (PMID 29085037, 2017).
SCN3A also shares sentences with these, for which no sentence is quoted: peripheral nerve injuries (7 papers); trigeminal neuralgia (5); developmental delay (4); injury (4); neuroma (4); diabetes (3); Intellectual disability (3); neurological disorders (3); spinal cord injury (3); channelopathies (2); diabetic neuropathy (2); Dravet syndrome (2); migraine (2); ovarian carcinoma (2); Pain (2); peripheral neuropathy (2); Alzheimer disease (1); Angelman syndrome (1); Arrhythmia (1); atrial fibrillation (1); Brain atrophy (1); brain disorder (1); Brugada syndrome (1); carcinoid (1); carcinoid syndrome (1); central nervous system diseases (1); Cognitive impairment (1); complex regional pain syndrome (1); congenital heart malformation (1); early infantile epileptic encephalopathy type 13 (1).
A further 17 diseases each share a sentence with SCN3A in 1 paper.